MIR4278 (microRNA 4278)
Synonyms: hsa-mir-4278
Gene: MicroRNA gene on chromosome 5 (6,827,853 to 6,827,921, reverse strand). Ensembl gene ENSG00000283420.
Diseases named in the same sentence as MIR4278 in open-access papers:
MIR4278 is named in the same sentence as 2 diseases in open-access papers, as found by Europe PMC text mining. Sharing a sentence is not in itself a finding about the gene and the disease.
MIR4278 shares sentences with these, for which no sentence is quoted: Cerebellar hypoplasia (1 paper); hypospadias (1).